BAG3 (BAG cochaperone 3)
Diseases named in the same sentence as BAG3 in open-access papers (continued):
Sharing a sentence is not in itself a finding about the gene and the disease.
tumor (continued). "BAG3 is an anti-apoptotic protein that has been shown to sustain cell survival in a variety of tumor types, and indeed its down-regulation appears to induce cell apoptosis and impair tumor growth also in SCLC cells suggesting that it may represent a novel target for therapy in positive tumours." (PMID 25149536, 2014). "Group 1 was saline as the control group, Group 2 was administered with BAG3-siRNA and given PLT, no inhibition of tumor growth versus saline was observed in this group, indicating no cytotoxic effect of laser or siRNA or laser alone." (PMID 37344887, 2023). "Group 5 animals were treated with BAG3-siRNA/GDNDs + PLT for 18 days and this group showed the maximum inhibition of tumor growth with tumor volume reduced by up to 3.8% with no resume of growth after the treatment ended." (PMID 37344887, 2023). "Upregulation of the anti-apoptotic genes BCL2L2, BAG3, and downregulation of pro-apoptotic genes DAXX, FAF1, PAK1, DFFA, ENDOG was found in reprogrammed tumours pointing to a cell cycle arrest without engagement of the apoptotic pathway." (PMID 29662623, 2018). "Group 3 was treated with BAG3-siRNA/GDNDs, without PLT.T the tumor growth in this group slightly reduces to 79.5% compared to the control, signifying the delivery of siRNA by GDNDs and tumor suppression effect after BAG3 gene silencing." (PMID 37344887, 2023).
myopathy (37 papers, 2011 to 2025). A disease of the muscle in which the muscle fibers do not function properly. "BAG3 is crucial for protein homoeostasis and myocyte contraction, with variants linked to HFpEF and myofibrillar myopathy." (PMID 41172738, 2025). "It thus appears that ZAKβ signalling is required for the turnover of certain proteins and those identified here, FLNC, BAG3 and Myotilin, are implicated in myofibrillar myopathies." (PMID 37427997, 2023). "At age 11, a mutation for a heterozygous variant (p.Pro290Leu) was found and she was diagnosed with myopathy due to BAG3 gene." (PMID 40757566, 2023). "The expanding panel of disorders associated with myofibrillar myopathies include BAG3, Desmin, Filamin C, Zasp, and all these proteins accumulate in cytoplasmic bodies." (PMID 40757566, 2023). "Mutations in BAG3 have been associated with dominant forms of myopathy affecting skeletal muscle and the heart." (PMID 35964012, 2022). "Recently, different morpholino-mediated knockdown studies in zebrafish showed that loss of Bag3 led to severe heart and skeletal muscle defects and (cardio-)myopathy." (PMID 33137814, 2020). "Naturally occurring mutations in the human bag3 gene are mostly associated with the development of myopathies." (PMID 28680391, 2017). "BAG3 null mutation mice show severe striated muscle degeneration and early lethality, characterized by myofibrillar myopathy." (PMID 21423662, 2011). "BAG3 is highly expressed in striated muscle and null mutations in BAG3 are implicated in myofibrillar myopathy." (PMID 21423662, 2011). "Mutations in DES, CRYAB, FLNC, LDB3, and BAG3 lead to myofibrillar myopathies and/or DCM." (PMID 39684857, 2024). "The data using targeted gene disruption in mice or BAG3-deficient mice to examine BAG3 function indicated deficiency in BAG3 would develop severe myopathy in Z-disk architecture and myofibrillar apoptosis implicating BAG3 contributes to maintaining the myofibrillar structure." (PMID 32751309, 2020). "Bag3 deficiency in mice resulted in fulminant myopathy and early lethality." (PMID 26545904, 2015). "Importantly, accumulation of aggregated proteins has been documented in the biopsies of patients affected by myopathy and peripheral neuropathy, further supporting the interpretation that these mutations may affect BAG3 PQC functions." (PMID 32472079, 2020). "Out of the known list of myofibrillar myopathy–related genes, only the protein quality control related candidates Dnajb6 and Bag3 were significantly up‐regulated in soleus muscle from both hetero‐ and homozygous R405W desmin mice at three months of age." (PMID 41165044, 2025). "Similar functional alterations are observed in the myofibrillar myopathy-related BAG3 p.P470S, which falls in the BAG domain." (PMID 36594740, 2023). "Like BAG3, HSPB8 mutations have been described in distal hereditary motor neuropathy, axonal Charcot-Marie-Tooth disease, and myopathies." (PMID 36594740, 2023).
myopathy (continued). "Immunofluorescence analysis of muscle sections from mice and a human biopsy showed evidence of FLNC and BAG3 accumulations as well as other myofibrillar myopathy markers." (PMID 37427997, 2023). "For example, DNAJB6 [log2 fold-change (log2FC) of 2.24] and the NEF chaperone BAG3 (log2FC of 3.13) lead to Limb-girdle muscular dystrophy 1E58 and myopathies, respectively." (PMID 33846299, 2021). "BAG3 gene deletion in mice leads to lethal myopathy, and overexpression of BAG3 protects the heart against I/R through the regulation of autophagy." (PMID 34943839, 2021). "The knockout of the bag3 gene in mice (by retroviral insertion) leads to a fulminant postnatal myopathy followed by death before 4 weeks of age." (PMID 28680391, 2017). "In Drosophila melanogaster the muscle integrity and muscular protein homeostasis is ensured by an analogous macroautophagy process (called CASA) that is mediated by the functional BAG3 ortholog starvin (see Impact of BAG3 on Myopathies)." (PMID 28680391, 2017). "MFM with cardiac transplant due to BAG3 myopathy in an 18-year-old girl." (PMID 40757566, 2023). "In addition, resemblance to other myofibrillar myopathies was observed as myotilin-positive myofibrillar lesions also contain BAG3 and HSPB8." (PMID 33974137, 2021). "Intriguingly, just like BAG3 mutations, mutations in DNAJB6 have been linked to myopathies as well." (PMID 30559338, 2018). "In addition, BAG3 protein co-localized with sites of desmin aggregation found in skeletal muscle from canine myofibrillar myopathy." (PMID 21423662, 2011). "Interestingly, BAG3 or αB-crystallin aggregation as well as aggregation of myofibrillar structural proteins like myotilin and desmin in the Ku + biopsies resemble aggregation in myofibrillar myopathies." (PMID 39012547, 2024). "The reported pathological features in all HSPB8-related myopathies have been similar: dystrophic changes and MFM pathology with protein aggregates (desmin, myotilin, CRYAB, dystrophin, HSPB8, DNAJB6, myotilin, BAG3, TDP-43, and ubiquitin) and rimmed vacuoles." (PMID 32093037, 2020). "We studied an Italian family with a 26-year-old female patient suffering from a BAG3 myopathy, her non-consanguineous asymptomatic healthy parents and her asymptomatic healthy brother." (PMID 27443559, 2016). "BAG3-deficient animals developed left ventricular dysfunction and early lethality and a fulminant myopathy characterized by noninflammatory myofibrillar degeneration with apoptotic features, whereas depressed bag3 expression in C2C12 myoblasts increased apoptosis." (PMID 32751309, 2020). "However, Bag2 knockdown in bag3+/+ or bag3+/- embryos did not result in (cardio-)myopathy." (PMID 33137814, 2020).
neurodegenerative disease (12 papers, 2011 to 2024). A disorder of the central nervous system characterized by gradual and progressive loss of neural tissue and neurologic function. "The reduced expression of BAG1 isoforms, decreased BAG1/BAG3 ratio, and association of BAG3 with NE supports our hypothesis of alternate NE peptide–induced aggrephagy machinery in these cells, a mechanism similar to neurodegenerative diseases." (PMID 39560992, 2024). "BAG3 can be involved in correct protein homeostasis during aging, and hence in the prevention of the development of neurodegenerative diseases." (PMID 38279266, 2024). "The involvement of BAG3 in selective macroautophagy-mediated degradation of tau and polyQ, contributes to the emergence and progression of neurodegenerative diseases such as AD and HD43–47." (PMID 31209204, 2019). "Therefore, the BAG1 to BAG3 protein ratio dictates a proteasome to autophagy switch in neurodegenerative diseases and has been shown to be critical for HSC homeostasis and aging." (PMID 39560992, 2024). "Mutations in BAG3, HSPB1, and CHIP have been linked to neurodegenerative diseases." (PMID 35164882, 2022). "Mutations in BAG3 and VCP genes are responsible for late onset degenerative diseases affecting skeletal muscle, suggesting that these proteins might play an important role in the maintenance of muscle cell homeostasis." (PMID 31481932, 2019). "Thus, BAG3-mediated macroautophagy has been considered as a potential therapeutic target for neurodegenerative diseases." (PMID 30675347, 2019). "HSPB1 and HSPB5 are upregulated in neurodegenerative diseases, especially in reactive glial cells and HSPB8, together with BAG3, is upregulated in astrocytes." (PMID 33330614, 2020). "Taken together, our results indicate that BAG3 is a potential modulator of the ALP, and therapeutic interventions targeting BAG3 may be sufficient to rescue dysfunction of the ALP seen in several neurodegenerative diseases with proteinaceous inclusions." (PMID 39394356, 2024). "BAG3 in concert with HSP70/HSC70 as well as the ubiquitin receptor p62/SQSTM1 specifically targets aggregation-prone proteins to autophagic degradation under conditions of cellular stress and in the context of aging and neurodegenerative diseases." (PMID 35164882, 2022).
infection (11 papers, 2008 to 2024). The state of being infected such as from the introduction of a foreign agent such as serum, vaccine, antigenic substance or organism. "Infection with EBOV can induce CMA autophagy in host cells mediated by Bcl-2–associated athanogene 3 (BAG3) protein." (PMID 35269494, 2022). "Clinical data from our study suggest that in BAG3 mutation carriers infection may trigger acute onset DCM with hemodynamic compromise." (PMID 25008357, 2014). "Clinical data from our study suggested that in BAG3 mutation carriers acute onset DCM with hemodynamic compromise may be triggered by infection." (PMID 25008357, 2014). "We established a model of BAG3 stable over-expression in HCT-116 cells by lentiviral infection to investigate the influence of BAG3 overexpression on HCT-116 cells." (PMID 30081850, 2018). "Results of our infection studies clearly reveal that overexpression of Bag3 inhibits expression of T-Ag, which in turn, negatively impacts the transcriptional activation of the viral late gene and virion formation." (PMID 22984599, 2012). "Infection of primary human foetal astrocytes with JCPyV resulted in the downregulation of BAG3 expression, whereas ectopic expression of LT in U-87 MG cells reduced BAG3 levels." (PMID 31408949, 2019). "Earlier studies have demonstrated that Bag3, a member of the Bcl-2-associated athanogene (Bag) family of proteins, which is implicated in autophagy and apoptosis, is downregulated upon JCV infection of glial cells and that JCV T-Ag is responsible for suppressing the activity of the BAG3 promoter." (PMID 22984599, 2012). "The siRNA 1659 specific for BAG3 was transfected into HEK293T cells for 48 h, which is followed by infection with WT and ΔUL56 PRV at an MOI of 0.05, respectively." (PMID 32365661, 2020). "In the performed infection assays, HEK293T cells were employed to investigate the effects of BAG3 overexpression or knockdown on lytic infection of PRV." (PMID 32365661, 2020). "The data from microarray analysis, 24 h post-infection, showed that EBNA3A expression induced a specific subset of chaperones and co-chaperones, including Hsp70, Hsp70B/B′, Bag3 and Hsp40." (PMID 18343826, 2008). "Collectively, these results supported a negative role of BAG3 during PRV lytic infection." (PMID 32365661, 2020). "Thus, the impact of Bag3 upon JCV T-Ag expression and its lytic infection may be considered as a host defense mechanism to halt the infection process." (PMID 22984599, 2012).
cardiac disease (7 papers, 2021 to 2025). "Third, since molecular functions of HSP22 are highly dependent on BAG3, therapeutic targeting of BAG3 has been considered as having potential in treating heart disease." (PMID 35011676, 2021). "Together, these results extend our understanding of the roles of BAG3 in heart disease beyond the cardiomyocyte-centric view and highlight the ability of tissue-engineered hiPSC models to elucidate cell type–specific aspects of cardiac disease." (PMID 39744939, 2025). "Among cardiac diseases, DCM is the most frequent but BAG3 variants represent only 0.3% of all DCM." (PMID 41378130, 2025). "However, heterozygous BAG3 knockout mice failed to recapitulate the clinical phenotypes of heterozygous BAG3 mutation-related cardiac disease." (PMID 34079803, 2021).
cardiovascular diseases (7 papers, 2014 to 2025). "Our data help to understand the cellular biology and molecular regulation of BAG3 expression in order to design new therapies for the treatment of patients with cardiovascular diseases." (PMID 27763645, 2016). "Therefore, we sequenced BAG3 gene in 70 TTC patients and in 81 healthy donors with the absence of evaluable cardiovascular disease." (PMID 26512958, 2015).
peripheral neuropathy (3 papers, 2018 to 2024). A disorder affecting the peripheral nervous system. "The variants CACNA1A c.6692G > A (NM_023035.2), BAG3 c.494C > T (NM_004281.3), and ITPR1 c.6692A > G (NM_001168272.1) did not segregate with the peripheral neuropathy phenotype." (PMID 31852952, 2019).
nervous system diseases (2 papers, 2023 to 2024). "A positive correlation between m1A modification and gene expression was observed, and we selected genes related to neurological diseases (Bag3, Csf1, Cyp1b1, Egfr, Flnc, Lox, Mt1, Nid2, Rab3b, and Tubb4a) for analysis, with MeRIP-RT-PCR and qRT-PCR performed to verify this phenomenon." (PMID 37173310, 2023).
neuromuscular disease (2 papers, 2020 to 2025). "In this review, we cover mutations in DNAJB6, DNAJB2, αB-crystallin (CRYAB, HSPB5), HSPB1, HSPB3, HSPB8, and BAG3, and discuss the molecular mechanisms by which they cause neuromuscular disease." (PMID 32093037, 2020). "Given the severity and rarity of BAG3-neuromuscular diseases (NMDs), series of patients are lacking." (PMID 40493734, 2025).
hematological disorders (1 paper, 2024). "Finally, the BAG3 protein, with its diverse regulatory activities in major intracellular processes, as well as its roles as a mediator of intercellular signaling, could be a target of significant interest in hematological disorders." (PMID 39198407, 2024).
skeletal muscle disorder (1 paper, 2011). A disease involving the skeletal muscle tissue. "DRMs are a growing class of skeletal muscle disorders caused by mutations in desmin, αB-crystallin, Z-band alternatively spliced PDZ motif, myotilin, filamin C, and Bag3." (PMID 21445271, 2011).
BAG3 also shares sentences with these, for which no sentence is quoted: lung carcinoma (5 papers); cardiac hypertrophy (3); osteosarcoma (3); Respiratory insufficiency (3); adenocarcinoma (2); arrhythmogenic right ventricular cardiomyopathy (2); catecholaminergic polymorphic ventricular tachycardia (2); chronic heart failure (2); endometrial cancer (2); gastric adenocarcinoma (2); liver cancer (2); lymphoma (2); Myocardial fibrosis (2); myocardial ischemia (2); peripartum cardiomyopathy (2); acute myocarditis (1); adenoma (1); advanced heart failure (1); alcohol dependence (1); alopecia (1); anemia (1); atrial fibrillation and flutter (1); autosomal dominant disease (1); axonal neuropathy (1); bacterial myocarditis (1); Barth syndrome (1); bladder cancer (1); bladder urothelial carcinoma (1); brain tumors (1); Brugada syndrome (1).
A further 80 diseases each share a sentence with BAG3 in 1 paper.